DKK3 (dickkopf Wnt signaling pathway inhibitor 3)
Diseases named in the same sentence as DKK3 in open-access papers (continued):
Sharing a sentence is not in itself a finding about the gene and the disease.
tumor (continued). "In particular, Dkk-3 is strongly expressed in tumor endothelial cells, and appears to be involved in capillary formation and angiogenesis." (PMID 28352232, 2017). "Promoter methylation has been identified as the principal mechanism of DKK3 silencing in multiple tumor types." (PMID 28249601, 2017). "Our study showed a significant decrease in DKK3 expression in 70% (25/37) of ACCs, strongly suggesting a tumor suppressor role for DKK3 in human adrenal tissue." (PMID 28249601, 2017). "Of note, human Dkk-3 was proposed to function as a tumor suppressor because its expression was shown to be down-regulated in cancer cells." (PMID 28352232, 2017). "Although implicated in zonal differentiation and hormone biosynthesis, a definitive role for the ubiquitous WNT inhibitor DKK3 in promoting functional differentiation and/or blocking tumor dedifferentiation of the adrenal cortex has yet to be clarified." (PMID 28249601, 2017). "Reduced expression in immortalized cells/Dickkopf-3 (REIC/Dkk-3) is a tumor suppressor and therapeutic gene in many human cancers." (PMID 27625116, 2016). "To validate the biological role of Dkk-3 other than a tumor suppressor, we examined the function of Dkk-3 in T24 cells." (PMID 27827955, 2016). "DKK3, a tumor suppressor in human tumorigenesis, was the most downregulated among all miR-25 target genes." (PMID 27801786, 2016). "Dickkopf-related protein 3 (Dkk-3) is a potential tumor suppressor reported in various cancer entities." (PMID 27827955, 2016). "Although GATA4 and DKK3 acted as tumor suppressors in most carcinomas, they promoted tumor progression in HB." (PMID 27788486, 2016). "Tumor sizes, volumes, and weights were lower in DKK3 shRNA group mice than in mice from either control group (negative control and non-transfected)." (PMID 27788486, 2016). "Our results thus demonstrate a novel mechanism by which this TF and miRNA co-regulate DKK3 expression and tumor cell growth." (PMID 27788486, 2016). "In conclusion, Dkk-3 has a novel role in the regulation of macropinocytotic and autophagic pathways, a distinct function of Dkk-3 other than a tumor suppressor." (PMID 27827955, 2016). "In the current study, we also noticed a modified cell morphology accompanied by a higher cell-matrix adhesion rate in one of our basal tumor models (MDA-MB-436) after stable re-expression of DKK3." (PMID 27467270, 2016). "Subsequently, we used these in vitro tumor models to analyze the effect of DKK3 re-expression on tumor cell behavior." (PMID 27467270, 2016). "In vitro studies reveal the impact of DKK3 on tumor growth, probably mediated by regulation of apoptosis, and on cell morphology modifications accompanied by changes on the molecular level." (PMID 27467270, 2016). "Dkk-3 suppresses tumor growth by the inhibition of Wnt signaling as an important signaling in tumorgenesis." (PMID 27329316, 2016). "Our studies show that DKK3 produced by MSCs is required to maintain a tumor-promoting environment by limiting CD8+ T cell but supporting M2-type macrophage infiltration." (PMID 26734010, 2015). "Human DKK3 was proposed to function as a tumor suppressor, since its expression is down-regulated in many types of cancer cells." (PMID 26689513, 2015). "Dickkopf homologue 3 (DKK3) gene which is located at 11p15, is proposed to function as a tumor suppressor gene since its expression is down-regulated in many types of cancer cells." (PMID 26689513, 2015). "In contrast, tumor-infiltrating CD8+ T cells were significantly increased in tumors containing DKK3−/− MSCs in comparison to tumors inoculated with WT MSCs or tumors without any MSCs (p < 0.0001 and 0.0076)." (PMID 26734010, 2015). "Here, we demonstrate that DKK3 is an additional important soluble factor for MSCs to regulate immune responses in the tumor microenvironment." (PMID 26734010, 2015).
tumor (continued). "Most importantly, the results in vitro were replicated in vivo, not only down‐regulating the expression of CD133 and β‐catenin but also increasing the expression of E‐cadherin in tumour tissues transfected with DKK3." (PMID 26395974, 2015). "When the REIC/Dkk-3 gene is overexpressed by Ad-REIC in the fibroblasts of the treated tumor, significant levels of IL-7 are expressed and secreted in the cells." (PMID 24527065, 2014). "The reduced expression in immortalized cells (REIC) gene is a tumor suppressor that is identical to the Dickkopf-3 (Dkk-3) gene." (PMID 24398705, 2014). "In our previous study, the therapeutic effects of the REIC/Dkk-3 gene as a tumor suppressor gene were determined by the development of an adenovirus vector carrying the human REIC/Dkk-3 gene (Ad-REIC)." (PMID 24527065, 2014). "Adenovirus-mediated REIC/Dkk-3 overexpression has been demonstrated to induce significant apoptosis in treated tumor sites and robust antitumor effects in mouse models." (PMID 24527065, 2014). "The anti-tumor effect of Ad-REIC depends on ER-stress-mediated JNK activation loaded by the overproduction of REIC/Dkk-3 protein, resulting in the induction of apoptosis." (PMID 24498395, 2014). "The Ad-REIC-induced synergistic secretion of REIC/Dkk-3 proteins and IL-7 cytokines at the treated tumor site is important for autologous cancer vaccination by the agent." (PMID 24527065, 2014). "We also found that the sequential treatment group induced re-expression or increased expression of the Wnt antagonist genes (SFRP1, HDPR1 and DKK3) in tumor cells of the subcutaneous AML mouse." (PMID 24923330, 2014). "Inoculation of Dkk-3-transfected 143B cell lines into nude mice showed significant decreased tumor growth and less metastatic pulmonary nodules (88.7%) compared to the control vector." (PMID 23476112, 2013). "ITIH5 and DKK3 proved to be candidate genes showing a significant correlation of the methylation pattern in paired tumor tissue DNA and cfDNA." (PMID 23320751, 2013). "Consistent with our in vitro experiments, Dkk-3 demonstrates a remarkable suppressive effect on tumor growth." (PMID 23476112, 2013). "Dkk-3 has been proposed to represent a novel tumor suppressor since gene expression is downregulated in various tumor cells 3–15 and hypermethylation of its promoter correlates with cancer occurrence 16–17." (PMID 23765731, 2013). "Differential display and real time PCR analysis revealed higher expression of a known tumor suppressor, Dickkopf homolog 3 (DKK3), by pubertal monkey Sc as compared to infant Sc." (PMID 23667645, 2013). "Ad-REIC/DKK3 has also been shown to induce an indirect host-mediated anti-tumor effect via the induction of IL-7." (PMID 23226679, 2012). "Expression of Dkk-3, a secreted putative tumor suppressor, is altered in age-related proliferative disorders of the human prostate." (PMID 22071168, 2011). "Dkk-3 has been proposed to represent a novel tumor suppressor since gene expression is downregulated in various tumor cells and hypermethylation of its promoter correlates with cancer occurrence." (PMID 22071168, 2011). "Up-regulation of VAV3 and TWIST1 oncogenes and repression of the DKK3 tumor-suppressor was observed in PC346DCC, suggesting a potential AR bypass mechanism." (PMID 20976069, 2010). "It was previously reported that expression of the Wnt antagonist genes WIF1 and DKK3 is downregulated in several tumor entities as a consequence of epigenetic DNA modification." (PMID 19570204, 2009). "Patients harboring DKK3 methylation in the tumor had a poor prognosis (54% chance of 10-years OS) in contrast to patients retaining an unmethylated DKK3 promoter, who had a favorable prognosis (97% chance of 10-years OS)." (PMID 19570204, 2009). "In contrast, DKK3 methylated tumours showed a significant mRNA downregulation (exp = 0.17; FC = 5.9) compared with DKK3 unmethylated tumours and normal breast tissue (global p < 0.001)." (PMID 18826564, 2008).
tumor (continued). "A significant downregulation of DKK3 mRNA expression in tumour tissue compared with its adjacent normal tissue was detected in 14 (74%) of the 19 pairs, as defined by an expression fold change of two or more (FC2)." (PMID 18826564, 2008). "To date, four SFRP family genes (SFRP1, SFRP2, SFRP4 and SFRP5) and two DKK family genes (DKK1 and DKK3) have been identified as targets of epigenetic silencing in human tumours." (PMID 18283316, 2008). "It was previously reported that expression of the putative Wnt antagonist DKK3 was downregulated in several tumour entities as a consequence of epigenetic DNA modification." (PMID 18826564, 2008). "In a mouse model, DKK3 proved to be a promising therapeutic agent to significantly inhibit tumour growth in testicular germ cell cancer." (PMID 18826564, 2008). "A boxplot illustrates the distribution and medians of DKK3 RNA expression among normal breast tissues, DKK3 unmethylated tumours and DKK3 methylated tumours." (PMID 18826564, 2008). "Of the targets identified, our interest was drawn to DKK3, which is a tumour suppressor and inhibits cell invasion." (PMID 18665176, 2008). "The frequency of DKK3 mRNA downregulation measured in this tumour cohort (27 of 40, 68% by FC2) is in good agreement to the result achieved with the 19 matched pairs." (PMID 18826564, 2008). "The median DKK3 expression level (exp) of unmethylated tumours (exp = 0.87; FC = 1.2) was comparable with that of normal breast tissues (set to exp = 1)." (PMID 18826564, 2008). "In support of an extended role for MT1-MMP, the results of this study offer further evidence of interaction with other targets, specifically with negative regulation of the antimigratory tumour suppressor gene DKK3 in UCC." (PMID 18665176, 2008). "DKK3 expression levels in the tumour and normal tissue groups were shown to be significantly different (p = 0.002; U-test), and DKK3 protein was also differentially expressed within the eight matched pairs (p < 0.001; t-test)." (PMID 18826564, 2008). "Dkk-3 locus methylation was detected in six ALL-derived cell lines and in 33% of tumours at diagnosis, indicating that inactivation of the Dkk-3 gene is a frequent and early event in the process of tumorigenesis in this disease." (PMID 15226763, 2004). "Together, these findings underscore the intricate and context‐sensitive role of DKK3, delaying oncogenesis during early stages while paradoxically promoting tumor progression in later stages, suggesting that therapeutic targeting strategies should be approached with caution." (PMID 41147409, 2026). "The re‐analysis of another publicly available pancreas single‐cell atlas, which includes samples from healthy donors, PDAC patients, and adjacent normal tissues, similarly revealed a notable increase in DKK3 expression in fibroblasts transitioning from the PanIN stage to tumor stage." (PMID 41147409, 2026). "In line, these mice already exhibited enlarged regions containing low‐grade pancreatic intraepithelial neoplasia (PanIN) lesions, whereas those were only rarely found in their age‐matched KC counterparts, suggesting a tumor suppressor role of DKK3 at the initiation stage." (PMID 41147409, 2026). "In various cancers, DKK3 may act as an oncogene through immunomodulation of the tumor microenvironment, and it could also explain its oncogenic function in EAC." (PMID 39795613, 2025). "Although we could show that DKK3-CP significantly suppressed tumor growth in this regimen as a pilot study, the ideal treatment regimen should be optimized in further investigations." (PMID 40917921, 2025). "The DKK3 complementary peptide (DKK3-CP) can inhibit cellular proliferation, migration, invasion, and in vivo tumor growth of the subcutaneously transplanted tumors with direct injection of DKK3-CP at low doses, and is thought to be a promising new therapeutic reagent." (PMID 40917921, 2025). "DKK3-CP showed tumor suppression effects comparable or superior to those of CDDP and Cmab." (PMID 40917921, 2025).
tumor (continued). "Although its role is not fully defined, DKK3 is implicated in angiogenesis and tumor progression, suggesting its potential as a CRC biomarker." (PMID 40806747, 2025). "In our previous study, we investigated “in vitro” and “in vivo” the biological role of DKK3 in tumor cells of GB, finding that a modulation of this protein could promote apoptosis, providing a potential strategy for the treatment of GB." (PMID 38612910, 2024). "Moreover, DKK3, TGFB1 and ECM1 have acted as immune-associated genes in the PCa tumour microenvironment." (PMID 38855324, 2024). "The variability in DKK3 levels across different populations could be due to differences in tumor microenvironments, which affect its production and utilization." (PMID 39766076, 2024). "Tumor-derived DKK3 regulates Tregs to inhibit CD8+ T cell function." (PMID 37847565, 2023). "One of the explanations for this finding is the fact that most of our patients (55.55%) were low–moderate Gleason grade PCa and previous reports found a negative association between DKK3 expression and tumor grade in various cancers." (PMID 36845147, 2023). "Canonical Wnt signaling also inhibits Treg activity; therefore, suppression of Wnt by tumor-derived DKK3 may mediate CD4+ cell differentiation toward Tregs." (PMID 37847565, 2023). "DKK-3 expression is elevated and exhibits tumor-promoting functions in some cancers." (PMID 38201279, 2023). "In summary, our study highlighted possible novel mechanisms and genes that are modulated by DKK3 that might help in improving our understanding of its tumor suppressor and protective role in PCa." (PMID 36845147, 2023). "The level of DKK3 expression is low in the majority of solid tumors and mediates cell apoptosis and/or cycle arrest in over-expression research of various cancer cell types, exerting a tumor-suppressive role of Wnt signaling regulators." (PMID 38269250, 2023). "DKK-3 acts as a tumor suppressor through inhibition of the Wnt/β-catenin signaling pathway." (PMID 38201279, 2023). "In particular, expression of DKK3 and PDPN was markedly increased in stroma-proximal regions and both are established markers of cancer-associated fibroblasts implicated in support of tumor growth." (PMID 37350578, 2023). "Treatments that inhibit DKK-3 in tumors could inhibit tumor-suppressive functions in healthy tissues." (PMID 38201279, 2023). "In the present study, the three markers from the fibrosome with the highest reported predictive values (APLP2, BNIP3L, CD59) and an additional well-known fibrosis marker (DKK3) in renal and cardiac disease were investigated on protein expression level in primary tumor samples." (PMID 35796776, 2023). "Finally, loss of SMAD4 in metastatic tumor organoids has increased secretion of DKK3, which inhibits NK cell activity, providing evidence of SMAD4 loss influencing tumor immune response." (PMID 38136364, 2023). "Thus, in human BC both the stroma and tumor cells themselves likely contribute DKK3 to the microenvironment." (PMID 37847565, 2023). "There are various strategies to increase DKK-3 levels, where it acts as a tumor suppressor." (PMID 38201279, 2023). "In addition, although DKK3 is known to have a tumor suppressive effect, DKK3 was well expressed in GBM in our study and was recently reported to have an oncogenic effect." (PMID 35599254, 2022). "Similarly, 3 markers (CFD, LEP and DKK3) were downregulated both in tumour lysates and plasma from patients with cancer." (PMID 34997107, 2022). "Moreover, MSCs exposed to radiotherapy showed increased expression and secretion of Dkk-3, and MSCs were shown to enhance the effects of radiotherapy on tumor growth in a mouse melanoma xenograft model." (PMID 36497305, 2022). "What’s more, we identified that DKK3 might be a downstream effector of ApoG2 exerting tumor suppressive effects in CC." (PMID 35924156, 2022).
tumor (continued). "Moreover, DKK3 over-expression resulted in significantly elevated tumor cell proliferation, migration, invasion and in vivo tumor growth via increased Akt phosphorylation, whereas stable knockdown of DKK3 showed completely opposing effects in HNSCC cells." (PMID 36376957, 2022). "However the correlation of DKK3 expression and disease progression is dependent on tumor type, and most examples from genetic mouse models highlight the pro-tumorigenic effects of Dkk-3 secreted by non-tumor cells, in particular, stromal and immune cells." (PMID 36497305, 2022). "Among DKK3, it may function as a tumor suppressor gene, in fact, its downregulation and methylation have been reported in many human cancers." (PMID 36203482, 2022). "In addition, DYNLT1 was previously considered an interaction partner of REIC/Dkk-3, inducing apoptosis through its role as a tumor suppressor in various cancer cell lines." (PMID 35919504, 2022). "As an important regulator of Wnt transduction in the canonical signaling pathway in tumours, Dickkopf-related protein 3 (DKK3) negatively regulates aerobic glycolysis [HK2, HIF-1α, GLUT-1, LDHA and 3-phosphoinositide-dependent protein kinase-1 (PDK-1)] in BxPC-3 cells." (PMID 36578477, 2022). "We also discuss how the activation or inhibition of Dkk-3, depending on tumor type and context, might be used to treat different types of cancers." (PMID 36497305, 2022). "In addition, ApoG2 treatment inhibited CC xenograft tumor growth and upregulated the protein levels of DKK3, cleaved caspase-3 and E-cadherin." (PMID 35924156, 2022). "The expression of the gene encoding Dickkopf-3 (DKK3; chromosome 11p15 in humans) is reduced in many tumor types as well as in many cancer cell lines and in immortalized cells, giving rise to the alternative name REIC (Reduced Expression in Immortalized Cells)." (PMID 36497305, 2022). "Taken together, these data suggested that ApoG2 exhibited the anti-tumor activity in vitro may through upregulating DKK3 expression." (PMID 35924156, 2022). "Dickkopf-3 (DKK3), a tumor suppressor, is frequently downregulated in various cancers." (PMID 35205672, 2022). "The immunohistochemistry confirmed the downregulation of DKK3 in tumor tissues." (PMID 35924156, 2022). "In addition to its Wnt inhibitory function, DKK3 is also characterized as a tumor suppressor because of its reduced expression in many types of malignancies." (PMID 36376957, 2022). "In the present study, inhibiting tumor cell glycolysis resulted in a decrease in lactic acid production, which indicated that DKK3 maybe enhanced the activation and proliferation of T cells by inhibiting tumor cell glycolysis." (PMID 34391478, 2021). "In addition, downregulation of DKK-3 has been correlated to tumor cell proliferation in several solid cancers and hematologic malignancies." (PMID 34451907, 2021). "In our previous study, we had identified tumor suppressive role of DKK3 in GBC cell lines." (PMID 33670899, 2021). "To further understand its tumor suppressor functions, we overexpressed DKK3 in 3 GBC cell lines." (PMID 33670899, 2021). "Moreover, like other DKK members, secreted DKK-3 is able to modulate T-cell immune responses, thereby supporting its role as a tumor microenvironment modulator." (PMID 34451907, 2021). "A member of the Wnt inhibitor family, evidence suggests DKK3 may act as a tumor suppressor in the metastatic setting in some cancers and is over-expressed, leading to cancer invasion, angiogenesis, and chemoresistance in others." (PMID 34503162, 2021). "In addition, DYNLT1 has previously been considered as an interacting partner of REIC/Dkk-3, inducing apoptosis through its action as a multiple cancer cell line tumor suppressor." (PMID 32039741, 2020).